BSPH1 (binder of sperm protein homolog 1)
Description:
Binds sperm in vitro and promotes sperm capacitation. Specifically promotes capacitation induced by high density lipoproteins (HDLs). Also binds heparin, phospholipid liposomes, and weakly to gelatin. Does not bind chondroitin sulfate B.
Synonyms: ELSPBP2; BSP1
Tractability: Antibody: UniProt places it where antibodies can reach, with high confidence; UniProt predicts a signal peptide or a membrane-spanning region; its Gene Ontology location is reachable by antibodies, with medium confidence.
Gene: Protein-coding gene on chromosome 19 (47,968,046 to 47,992,170, reverse strand). Ensembl gene ENSG00000188334.
Subcellular location: Secreted
Gene Ontology:
Molecular function: heparin binding
Biological process: sperm capacitation
Cellular component: cell surface; non-collagenous component of interstitial matrix; extracellular region
Genetic constraint (gnomAD): Loss-of-function variants: 15 observed, 16.08 expected, observed/expected ratio (o/e) 0.93, 90% interval 0.62 to 1.43. The upper end of that interval is the gene's LOEUF score, 1.43, which puts it in group 5 of 6, group 1 being the genes least tolerant of losing a copy. Missense variants: 101 observed, 111.88 expected, observed/expected ratio (o/e) 0.9, 90% interval 0.77 to 1.07. Synonymous variants: 29 observed, 38.5 expected, observed/expected ratio (o/e) 0.75, 90% interval 0.56 to 1.03.
Homologues: Orthologues: chimpanzee BSPH1 (97% identical), chimpanzee BSPH1 (91% identical), macaque BSPH1 (67% identical), pig BSPH1 (52% identical), rabbit BSPH1 (50% identical), rat Bsph1 (50% identical), mouse Bsph1 (49% identical). Paralogues in human: ELSPBP1 (30% identical).
Diseases named in the same sentence as BSPH1 in open-access papers:
BSPH1 is named in the same sentence as 1 disease in open-access papers, as found by Europe PMC text mining. Sharing a sentence is not in itself a finding about the gene and the disease. The quoted sentences say what the papers report.
Infertility (1 paper, 2020). "In this study, both the Bsph1 and Bsph2 genes were deleted and no subfertility or infertility phenotype was observed." (PMID 32488144, 2020).